SNORD18 (Small nucleolar RNA SNORD18 )
Synonyms: LOC124903590
Gene: Small nucleolar RNA gene on chromosome 15 (90,755,243 to 90,755,312, reverse strand). Ensembl gene ENSG00000200677.
Gene Ontology:
Biological process: RNA processing
Cellular component: nucleolus
Homologues: Orthologues: chimpanzee SNORD18 (99% identical), macaque SNORD18 (96% identical), tropical clawed frog SNORD18 (73% identical), zebrafish SNORD18 (63% identical). Paralogues in human: SNORD18C (83% identical), SNORD18 (81% identical), SNORD18B (81% identical), SNORD18A (71% identical).
Diseases named in the same sentence as SNORD18 in open-access papers:
SNORD18 is named in the same sentence as 1 disease in open-access papers, as found by Europe PMC text mining. Sharing a sentence is not in itself a finding about the gene and the disease.
SNORD18 shares sentences with these, for which no sentence is quoted: schizophrenia (1 paper).